LAMC2 (laminin subunit gamma 2)
Diseases named in the same sentence as LAMC2 in open-access papers (continued):
Sharing a sentence is not in itself a finding about the gene and the disease.
neuroblastoma (1 paper, 2018). Neuroblastoma (NB) is the most common solid, extracranial childhood tumor. "Specifically, females and children younger than 18 months with specific genotypes in the lnc-LAMC2–1:1 rs2147578 C > G polymorphism are at an increased risk of neuroblastoma." (PMID 30285664, 2018). "We found that the lnc-LAMC2–1:1 rs2147578 C > G polymorphism is associated with increased neuroblastoma susceptibility." (PMID 30285664, 2018). "We investigated the association between the lnc-LAMC2–1:1 rs2147578 C > G polymorphism and neuroblastoma susceptibility in Chinese Han populations." (PMID 30285664, 2018). "The Lnc-LAMC2–1:1 rs2147578 C > G polymorphism is associated with increased neuroblastoma susceptibility in Han populations of Northern China." (PMID 30285664, 2018). "In this study, we investigated the association between the lnc-LAMC2–1:1 rs2147578 C > G polymorphism and neuroblastoma susceptibility in Chinese Han populations." (PMID 30285664, 2018). "However, the lnc-LAMC2–1:1 rs2147578 C > G polymorphism was associated with increased neuroblastoma risk in the Henan population (CG vs. CC: adjusted OR = 1.73, 95% CI = 1.03–2.89, P = 0.048; CG/GG vs. CC: adjusted OR = 1.64, 95% CI = 1.004–2.68, P = 0.048)." (PMID 30285664, 2018). "Here we hypothesized that the lnc-LAMC2–1:1 rs2147578 C > G polymorphism may contribute to neuroblastoma susceptibility, and we tested our hypothesis via a case-control study." (PMID 30285664, 2018). "The Lnc-LAMC2–1:1 rs2147578 C > G polymorphism may contribute to increased neuroblastoma susceptibility in children of Henan province." (PMID 30285664, 2018). "Our results show that the lnc-LAMC2–1:1 rs2147578 C > G polymorphism may also be involved in neuroblastoma tumorigenesis." (PMID 30285664, 2018). "Combined analysis revealed that the lnc-LAMC2–1:1 rs2147578 C > G polymorphism was associated with increased neuroblastoma susceptibility (CG vs. CC: adjusted OR = 1.33, 95% CI = 1.01–1.75, P = 0.045; CG/GG vs. CC: adjusted OR = 1.34, 95% CI = 1.03–1.74, P = 0.028)." (PMID 30285664, 2018). "The possible interaction between the lnc-LAMC2–1:1 rs2147578 polymorphism and the EGFR pathway may account for the increased risk of neuroblastoma of the G allele." (PMID 30285664, 2018). "In addition, children with lnc-LAMC2–1:1 rs2147578 CG/GG genotypes were prone to develop earlier stages of neuroblastoma (adjusted OR = 1.46, 95% CI = 1.01–2.12, P = 0.046)." (PMID 30285664, 2018).
ovarian serous carcinoma (1 paper, 2021). "LAMC2 expression was upregulated in SKOV-3 (ovarian serous carcinoma cell line) compared with MCV152 (benign ovarian epithelial tumor line)." (PMID 34512203, 2021).
pituitary adenoma (1 paper, 2023). "SLC2A1, CLDN4, LAMC2, S100A4, and ITGB3 were significantly correlated with the invasiveness of pituitary adenoma (P<0.05)." (PMID 36936141, 2023).
polyp (1 paper, 2024). A usually exophytic mass attached to the underlying tissue by a broad base or a thin stalk. "Finally, through IF staining, we also revealed increased levels of TGFBI and LAMC2 in all three polyp subtypes." (PMID 38264936, 2024).
scleroderma (1 paper, 2022). Scleroderma is a rare autoimmune connective tissue disorder characterized by abnormal hardening of the skin and, sometimes, other organs. "In contrast to the untreated scleroderma mice group, the ability of endothelial development associated proteins (LAMC2, PLOD3, and TP63) recovered in the treatment group." (PMID 35315234, 2022).
Stroke (1 paper, 2022). Sudden impairment of blood flow to a part of the brain due to occlusion or rupture of an artery to the brain. "Weaker evidence was found for GP1BA, VCAM1 and LAMC2 as potential drug targets for stroke, with evidence for colocalization in only one pQTL dataset." (PMID 36180795, 2022). "Using public drug databases, we curated drugs targeting those proteins in a direction compatible with a beneficial therapeutic effect against stroke based on MR estimates and identified such drugs for VCAM1, F11, KLKB1, GP1BA, LAMC2 (inhibitors) and PROC (activators)." (PMID 36180795, 2022).
transitional cell carcinoma (1 paper, 2020). A malignant neoplasm arising from the transitional epithelium, usually affecting the urinary bladder, ureter, or renal pelvis. "Based on betweenness centrality and survival analysis, we identified laminin subunit gamma-2 (LAMC2) in the grade 2 carcinoma, gelsolin (GSN) in the grade 3 carcinoma, and homeodomain-interacting protein kinase 2 (HIPK2) in the transitional cell carcinoma lymphatic metastasis." (PMID 32640634, 2020). "According to the results of the betweenness and survival analysis in four disease types, LAMC2, GSN, and HIPK2 may respectively be the potential regulator in cell lines with grade 2 carcinoma, grade 3 carcinoma, and transitional cell carcinoma lymphatic metastasis." (PMID 32640634, 2020).
tumor (132 papers, 2007 to 2026). "Clinically, a high LAMC2 expression was associated with poor tumor differentiation, advanced TNM staging, and reduced 3-year survival rates." (PMID 41952674, 2026). "To validate this finding, we performed immunofluorescence staining against tumor-associated Laminins (human Laminin Subunit Gamma 2, hLAMC2) in dECM-tumor sections and observed that hLAMC2 strongly colocalized with the tumor cell presence (I left)." (PMID 40166338, 2025). "LAMA3, LAMB3 and LAMC2 genes encode for laminin-332, which is related to tumor invasiveness and metastasis and is considered a factor of poor prognosis." (PMID 38473784, 2024). "In the unifactorial analysis, the T stage, tumor recurrence, and LAMC2 expression were found to be significantly associated with DFS." (PMID 38703300, 2024). "LAMC2, encoding a laminin subunit, is a critical component of the laminin-5 complex involved in regulating cell adhesion, migration, and tumor microenvironment remodeling." (PMID 39850570, 2024). "Increasing evidence indicates that the high invasive potential and distant metastasis of tumor cells is dependent on LAMC2 expression, which is closely associated with tumor metastasis, recurrence, and patient mortality." (PMID 37415741, 2023). "As CXCL1 and LAMC2 are associated with recruitment of neutrophils and macrophages into tumor tissue, these results demonstrate the significant role of immune cell population in LUAD growth." (PMID 36973297, 2023). "LAMC2 is closely associated with various biological processes, including cell adhesion and tumor cell migration." (PMID 35506252, 2022). "Higher levels of expression of mesenchymal-associated genes SNAI1, SERPINE1, MSN, NRP1 and LAMC2 were observed in CTCs compared to primary tumour in three of the four models (the exception being LuCaP96)." (PMID 34206049, 2021). "Aberrant over-expression of LAMC2 was associated with poor prognosis of PC patients, tumor status and subtypes." (PMID 34606473, 2021). "By calculated the correlation coefficient of GPR115 and ECM/Focal adhesion related genes, we found that LAMC2, the highest relevant gene, was remarkedly elevated in tumor tissues and positively associated with poor prognosis." (PMID 33330053, 2020). "The expression of LAMA3 and LAMC2 was found to be upregulated in PDAC tumor tissues in the 9 datasets, with a favorable diagnostic ability for distinguishing between PDAC and non-tumor tissues." (PMID 31182680, 2019). "LM-332 (encoded by LAMA3, LAMB3, and LAMC2) has been linked to tumor invasiveness in various types of cancer." (PMID 29426928, 2018). "In these studies, CDH1 loss and overexpression of SNAI1, TWIST1 and LAMC2 were observed at the invasive front of the tumors, particularly in single or cords of tumor cells detaching from the tumor mass." (PMID 26214683, 2015). "LAMC2 constitutes a diagnostic and prognostic biomarker in neoplasias." (PMID 40725121, 2025). "Collectively, these results indicate that hypoxia could reverse the tumor suppressor which were caused by attenuated LAMC2 expression." (PMID 38989468, 2024). "Moreover, LAMC2 overexpression was associated with lymphnode metastasis and tumor-node-metastasis stages." (PMID 37174083, 2023). "According to these data, we hypothesized that the expression of LAMC2 may lead to an increased risk of tumor recurrence." (PMID 34606473, 2021). "Promoter hypomethylation in tumor tissues correlated with overexpression of LAMC2, CTHRC1, CXCL13, FST, SPP1, and PLAU, whereas CDKN2A showed hypermethylation." (PMID 41776121, 2026). "VE-cadherin is essential for VM channel stability, LAMC2 mediates extracellular matrix (ECM)–tumor interactions, and MMP-2 facilitates ECM degradation to enable invasion and channel formation." (PMID 41463012, 2025). "TGF-β1 was expressed in the deepest tumor cells and was weakly positive in the stroma, and LAMC2 was also highly expressed in the deepest tumor cells." (PMID 40244200, 2025).
tumor (continued). "At the cellular level, LAMC2 knockdown significantly inhibited tumor cell migration and invasion capabilities, while also reducing the expression of key molecules associated with integrin signaling pathways." (PMID 40470730, 2025). "Our findings uncover potential therapeutic targets such as LAMC2, which promotes tumor invasiveness." (PMID 40470730, 2025). "The current IHC results showed that TGF-β1 was expressed in tumor cells in the deepest area of tumor invasion, where TB was observed, and LAMC2 was expressed in TB-expressing cells and tumor cells bordering the stroma." (PMID 40244200, 2025). "The identification of LAMC2 as a key driver of tumor invasiveness highlights its potential as a therapeutic target in PSCC." (PMID 40470730, 2025). "Functional validation of Tum_1 markers, particularly LAMC2, in preclinical models will be critical to confirm their role in tumor progression and treatment response." (PMID 40470730, 2025). "Ligand-receptor pairs linked to high-risk tumors, including IL1A_IL1RAP, COL5A1_ITGB1, APP_NCSTN, PLAU_ITGA5, AGRN_ITGB1, and LAMC2_ITGA6, were found to be particularly enriched in tumor regions." (PMID 40021759, 2025). "Laminin 332 is a high affinity receptor for integrins A6B1, A6B4 and A3B1, and genetic manipulation of levels of LAMC2 is known to control cell migration, as well as contribute to the stem cell niche and an immune-suppressive tumor microenvironment." (PMID 39496753, 2024). "Quantitative data consistently showed that LAMC2 staining was significantly higher in iCCA tumor tissues versus bile duct cells, hepatocytes, and HCC tumors, respectively (p < 0.001 for each comparison)." (PMID 38526177, 2024). "Immunohistochemistry staining of the tumor tissues showed that LAMC2 overexpression effectively reduced GRP78, and promoted Ki67 protein levels." (PMID 37891404, 2024). "Meanwhile, overexpressed of LAMC2 markedly advanced Ki-67 activity in tumor tissues compared to control." (PMID 38989468, 2024). "Findings demonstrated that LAMC2 knockdown led to a substantially reduced tumor growth rate and volume compared to the control (p < 0.01)." (PMID 38703300, 2024). "Then, we developed a novel diagnostic model using LAMC2, SLC6A14 and CTSE, which showed a strong predictive ability in screening PC specimens from non-tumor specimens in several GEO datasets." (PMID 38267509, 2024). "LAMC2 can also modulate tumor microenvironment by regulating macrophage infiltration and extracellular matrix remodeling in NSCLC." (PMID 37891404, 2024). "In other words, LAMC2 overexpression efficiently impeded the tumor-inhibiting effect of tunicamycin." (PMID 37891404, 2024). "Following this, the impact of ectopic expression of LAMC2 in NSUN2-depleted HNSCC cells was assessed by using a xenograft tumor model." (PMID 39595099, 2024). "In effort to understand the molecular mechanism of LAMC2 on mitigating ER stress and maintaining normal mitochondrial function in tumor cells, IP-MS was used to detect LAMC2-binding proteins in A549 cells." (PMID 37891404, 2024). "In order to prove that ER stress promotes the formation of LAMC2/MYH9/MYH10 complexes, tunicamycin was used to treat tumor cells, and the results showed that the expression of LAMC2, MYH9, MYH10, GRP78 and DRP1 was significantly increased." (PMID 37891404, 2024). "Laminin-5 is the main ligand of integrin α6β4, and the binding of integrin β4 to LAMC2 facilitates tumor metastasis through FAK." (PMID 38475740, 2024). "In two HDTV orthotopic iCCA mouse models driven by AKT/NICD and AKT/YapS127A, silencing mouse LAMC2 using shRNA significantly reduced iCCA tumor formation." (PMID 38526177, 2024). "MYH9 and MYH10 silencing were also shown to reverse the proliferative effects of LAMC2 overexpression on tumor cells." (PMID 37891404, 2024). "In vivo, overexpressing either the human LAMC2 or the active human EGFRL858R both partially rescued shLAMC2‐mediated tumor suppression in the AKT/YapS127A‐induced HDTV iCCA mouse model." (PMID 38526177, 2024).
tumor (continued). "The results showed that mice in the AKT/YapS127A/LAMC2 control group developed observable massive tumors, while AKT/YapS127A/LAMC2 mice with Gefitinib treatment had much less tumor formation." (PMID 38526177, 2024). "The impact of LAMC2 knockdown was also investigated and revealed a notable decrease in Ki67 expression, indicating that the suppression of LAMC2 effectively reduced the capacity of tumor proliferation in the mouse model." (PMID 38703300, 2024). "IHC analysis exhibited markedly enhanced staining intensity of LAMC2 in GC tumor tissues (p < 0.001)." (PMID 38703300, 2024). "Specifically, knockdown of LAMC2 increased ROS and decreased mitochondrial membrane potential, while overexpression of LAMC2 significantly reduced free radical levels in tumor cells and increased mitochondrial membrane potential." (PMID 37891404, 2024). "To examine the ability for LAMC2 to combat ER stress and promote tumor growth in vivo, we analyzed the real-time tumor growth in nude mice injected with either control or LAMC2 plasmid A549 cells treated with tunicamycin." (PMID 37891404, 2024). "We found that LAMC2 is mainly localized to the ER in tumor cells, and under ER stress, both LAMC2 and GRP78 expressions were elevated." (PMID 37891404, 2024). "In contrast, LAMC2 overexpression substantially accelerated tumor growth, resulting in significantly larger tumor sizes than the control (p < 0.01)." (PMID 38703300, 2024). "Taken together, these data demonstrated a specific high expression of LAMC2 in iCCA tumor tissues within the liver." (PMID 38526177, 2024). "A mouse tumor xenograft model has been developed to explore the action of LAMC2 in controlling the metastasis of GC." (PMID 38703300, 2024). "Quantitatively, silencing LAMC2 largely reduced the iCCA tumor burden, shown through remarkable decreases in liver/body ratios, tumor numbers, and tumor sizes in both iCCA models (p < 0.01 for each comparison)." (PMID 38526177, 2024). "Herein, we identified the expression of LAMC2 was significantly increased under hypoxia, and showed that LAMC2 promoted tumor progression in vitro and in vivo, which was consistent with the role of hypoxia." (PMID 38989468, 2024). "LAMC2 downregulation can decrease tumor proliferation, metastasis, and invasion, as well as simultaneously inhibit tumor proliferation, metastasis, and invasion by disrupting autophagy homeostasis." (PMID 37415741, 2023). "Specifically, of the 25 tumor samples showing high LAMC2 staining, 33 showed medium, and 15 showed low LAMC2 staining." (PMID 37542131, 2023). "A cell line-derived xenograft (CDX) model was used to detect the effect of LAMC2 on tumor growth in vivo." (PMID 37415741, 2023). "Our findings showed that the effectiveness of gefitinib to reduce cancer cell activity, colony growth, and tumor growth in vivo was highly dependent on LAMC2 expression levels." (PMID 37542131, 2023). "This suggests that the tumor reduction effect of gefitinib was extremely effective in the LAMC2 overexpression group." (PMID 37542131, 2023). "Among the positively correlated gene sets, PLAU and LAMC2 were more strongly expressed in tumour samples than in normal samples." (PMID 37325056, 2023). "Tumor size, volume, and weight were highest in the control group, and lowest in the LAMC2 knockdown group." (PMID 37542131, 2023). "LAMC2 overexpression was also found in cancer cells and therefore the correlation between tumorigenesis and tumor spread and the protein levels was investigated." (PMID 37174083, 2023). "After oe-UCA1 treatment, the tumor volume and tumor weight in mice had clearly increased, but this effect was abrogated by sh-LAMC2." (PMID 36483681, 2022). "The results showed that the expression levels of ITGA2, ITGB6, LAMA3, LAMB3, and LAMC2 are significantly correlated with the tumor stage of PAAD patients, while the expression levels of COL1A2 are not correlated with the tumor stage of PAAD patients." (PMID 35899199, 2022).